LINC01610 (long independently transcribed non-coding RNA 1610)
Synonyms: EVADR
Gene: Long non-coding RNA gene on chromosome 6 (70,375,762 to 70,403,117, forward strand). Ensembl gene ENSG00000237643.
Diseases named in the same sentence as LINC01610 in open-access papers:
LINC01610 is named in the same sentence as 9 diseases in open-access papers, as found by Europe PMC text mining. Sharing a sentence is not in itself a finding about the gene and the disease.
LINC01610 shares sentences with these, for which no sentence is quoted: adenocarcinoma (2 papers); cancer (2); colorectal cancer (2); colorectal tumor (2); chronic myeloid leukemia (1); colon cancer (1); pancreatic adenocarcinoma (1); rectal tumor (1); tumor (1).